Y_RNA (Y RNA )
Gene: Miscellaneous RNA gene on chromosome 1 (155,120,490 to 155,120,598, forward strand). Ensembl gene ENSG00000202027.
Homologues: Orthologues: chimpanzee Y_RNA (99% identical), macaque Y_RNA (94% identical), guinea pig Y_RNA (85% identical), guinea pig Y_RNA (83% identical). Paralogues in human: RNY1 (90% identical), Y_RNA (87% identical), Y_RNA (86% identical), RNY1P11 (85% identical), Y_RNA (85% identical), Y_RNA (84% identical), Y_RNA (83% identical), Y_RNA (82% identical), RNY1P8 (81% identical), Y_RNA (81% identical), RNY1P5 (80% identical), Y_RNA (80% identical), and 95 more.